TRAJ23 (T cell receptor alpha joining 23)
Gene: T-cell receptor joining (J) gene on chromosome 14 (22,520,416 to 22,520,478, forward strand). Ensembl gene ENSG00000211866.
Diseases named in the same sentence as TRAJ23 in open-access papers:
TRAJ23 is named in the same sentence as 1 disease in open-access papers, as found by Europe PMC text mining. Sharing a sentence is not in itself a finding about the gene and the disease.
TRAJ23 shares sentences with these, for which no sentence is quoted: cancer (1 paper).